PSEN2 (presenilin 2)
Diseases named in the same sentence as PSEN2 in open-access papers (continued):
Sharing a sentence is not in itself a finding about the gene and the disease.
cancer (21 papers, 2005 to 2025). A tumor composed of atypical neoplastic, often pleomorphic cells that invade other tissues. "The top-scoring genes recurring in the four gene sets included key cancer genes, KAT2A, SKP1, FZD1, JAG1 and PSEN2." (PMID 28473661, 2017). "Sutcliffe showed that reducing presenilin-2 by administration of a cancer therapeutic that does not cross the blood–brain barrier reduced accumulation of Aβ in both blood and brain." (PMID 34520451, 2021). "Furthermore, in cancer cells, intracellular domain of EpCAM cleaved by TACE and presenilin-2 accelerates cell proliferation through the activation of β-catenin signaling." (PMID 22194864, 2011). "However, studies on the relationship between PSEN2 and cancer are still lacking, and whether PSEN2 plays similar roles in other tumors is still unknown." (PMID 37928268, 2023).
neurodegenerative disease (17 papers, 2012 to 2025). A disorder of the central nervous system characterized by gradual and progressive loss of neural tissue and neurologic function. "Lastly, PSEN2 Thr421Met may interact with other mutations in neurodegenerative disease related genes, which were found in the proband patient, such as ATP binding cassette subfamily A member 7 (ABCA7), Notch Receptor 3 (NOTCH3), or Leucine-rich repeat kinase 2 (LRRK2)." (PMID 36362122, 2022). "As for the other neurodegenerative diseases, familial forms (FAD) account for only a minority of cases and the most common mutations are found in presenilin 1 (PSEN1), presenilin 2 (PSEN2), and the amyloid precursor protein (APP)." (PMID 39273694, 2024). "No additional pathogenic mutations were found in other dominant causative genes of AD, FTD, or of other neurodegenerative diseases, such as APP, PSEN2, PRNP, PGRN, or MAPT." (PMID 30917570, 2019). "About half of the neurodegenerative disease-associated genes, namely APP, PSEN1, and PSEN2 for AD; C9orf72 and MAPT for FTD and SNCA; and PRKN and PARK7 for PD, have larger number of DPI robust TSSs than annotated CAT CAGE clusters." (PMID 30610612, 2019). "No additional pathogenic mutations were identified in other dominant causative genes of AD, FTD, or of other neurodegenerative diseases, such as PSEN1, PSEN2, PGRN, or MAPT on this patient." (PMID 30917570, 2019). "In general, endothelial CD147 deficiency reduces the expression of core AD genes, including App, Psen2, and Ifitm3, and we hypothesize that CD147 is a promising risk factor for AD and other neurodegenerative diseases." (PMID 33987940, 2021). "AD is a non-curable neurodegenerative disease with the majority of cases (85–90%) being sporadic and just 10–15% familial and caused by mutations in key genes such as Amyloid Precursor Protein (APP), Presenilin 1 (PSEN1), and Presenilin 2 (PSEN2), involved in the metabolic pathway of APP." (PMID 36231055, 2022).
brain disease (2 papers, 2016). "Apolipoprotein E (ApoE), Presenilin-1 (PSEN1) and Presenilin-2 (PSEN2), amyloid precursor protein (APP) and the linked mutations are some of the strongest risk factors that were observed to be associated with the brain disorder, Alzheimer’s." (PMID 27756223, 2016).
movement disorder (1 paper, 2021). Neurological conditions resulting in abnormal voluntary or involuntary movement, which may impact the speed, fluency, quality and ease of movement. "Interestingly, the clinical manifestation of patients with PSEN2 mutations at amino acid residue M239 showed high heterogeneity, including memory decline, language impairment, mental and behavior change, and sensory and movement disorders." (PMID 34389718, 2021).
neurogenetic disease (1 paper, 2024). "Among the four, PSEN1 and PSEN2 are known AD-related genes, reported in AlzGene, while C9orf72 and SOD1 are known to be relevant to neurogenetic disease and possess AD-relevant literature support in GeneCards." (PMID 38627848, 2024).
PSEN2 also shares sentences with these, for which no sentence is quoted: tumor (21 papers); Parkinson disease (7); HIV-1 infection (5); Huntington disease (4); neurological disease (4); Obesity (4); bladder cancer (3); cerebral amyloid angiopathy (3); COVID-19 (3); HCMV infection (3); late-onset Alzheimers disease (3); prion disease (3); adenovirus infection (2); AIDS (2); autosomal dominant disease (2); genetic disorder (2); glaucoma (2); glioblastoma (2); hippocampal atrophy (2); influenza (2); lung adenocarcinoma (2); prostate carcinoma (2); respiratory disease (2); Acute encephalopathy (1); amyloid‐positive (1); aortic valve stenosis (1); asthma (1); atherosclerosis (1); CADASIL (1); cardiovascular disease (1).
A further 44 diseases each share a sentence with PSEN2 in 1 paper.